INS (insulin)
Diseases named in the same sentence as INS in open-access papers (continued):
Sharing a sentence is not in itself a finding about the gene and the disease.
Hypoglycemia (continued). "In insulin-treated (T1DM and advanced T2DM) diabetic patients the sympatho-adrenal response (SAR) is the main defence against hypoglycaemia." (PMID 19442093, 2009). "One of the most commonly mentioned and feared adverse effects of IIT is severe hypoglycaemia, which occurs significantly more often when using IIT compared with conventional insulin therapy." (PMID 18939991, 2008). "During insulin-induced hypoglycemia, GLP-2 did not compromise nor potentiate the counterregulatory glucagon response or responses of the counterregulatory hormones norepinephrine and growth hormone." (PMID 41541287, 2026). "Despite subsequent insulin dose reduction, CGM detected nocturnal and early-morning hypoglycemia." (PMID 41536580, 2026). "In summary, in a rat model of insulin-treated T2D, daily SSTR2a administration increased glucagon counterregulation to hypoglycemia without worsening overall insulin sensitivity or glycemic control." (PMID 41502124, 2026). "Despite episodes of hypoglycemia requiring discontinuation of insulin, his triglyceride (TG) levels steadily declined without the need for plasmapheresis or surgical intervention." (PMID 42093778, 2026). "The purpose of this study was to assess the effects of daily SSTR2a administration for up to 11 days on overall glycemia and glucagon responses, in a male rat model of insulin-treated T2D, with and without hypoglycemia." (PMID 41502124, 2026). "CFTR modulators effect on hypoglycemia: CFTR modulators, particularly ivacaftor (IVA), have been shown to improve insulin secretion in PwCF—most notably in those carrying gating mutations such as G551D—suggesting potential restoration of islet function and improved glucose regulation." (PMID 41552835, 2026). "While severe episodes are uncommon, nonsevere hypoglycemia is frequently observed during insulin use and hospitalization." (PMID 41552835, 2026). "Studies indicate that 16%–58% of PwCFRD receiving insulin or other glucose‐lowering treatments experience nonsevere hypoglycemia, with some reporting multiple weekly episodes." (PMID 41552835, 2026). "This may be attributed to more precise insulin titration guided by patterns identified through CGM data, as well as a reduction in overcorrection of glucose levels following fewer episodes of hypoglycaemia." (PMID 41254466, 2026). "Liraglutide has been shown to preserve C-peptide AUC leading to fewer episodes of hypoglycaemia and increased time without need for insulin treatment." (PMID 41355468, 2026). "No systemic side effects, such as hypoglycemia or hypokalemia, were detected, consistent with prior safety data on topical insulin tested at the lower 100 u/ml concentration." (PMID 41584099, 2026). "However, PRE specifically reduced hypoglycemia exposure and triglycerides, while POST showed a marginal insulin-lowering trend." (PMID 41362785, 2026). "Compared with individuals without hypoglycaemia, individuals with post-OGTT hypoglycaemia had a significantly lower BMI and higher insulin sensitivity, without differences in beta cell function." (PMID 41896315, 2026). "While mortality was not reduced in insulin-treated COVID-19 patients even in the absence of hypoglycemia." (PMID 40469441, 2025). "Surprisingly, however, the baby’s 25-year-old mother had the same high titre of IAA as well as extremely high serum insulin levels, yet she was asymptomatic and did not suffer from any hypoglycaemia episodes." (PMID 41349642, 2025). "Collectively, after taking fenofibrate, it may be possible to increase the insulin level in the blood by activating FFA1, which may contribute to hypoglycemia as an adverse reaction." (PMID 41282005, 2025). "In general, insulin should be prescribed in the largest amount the patient can safely tolerate without hypoglycemia to counteract the catabolic effect of insulin insufficiency." (PMID 40533897, 2025).
Hypoglycemia (continued). "The patient received a basis bolus regime of insulin and over the following 6 years no episodes of severe hypoglycaemia or DKA occurred." (PMID 40135138, 2025). "Diazoxide was not appropriate for this patient's hypoglycemia as initial laboratory data indicated suppression of endogenous insulin as well as concern that his blood pressures would not tolerate diazoxide-mediated vasodilation." (PMID 40727482, 2025). "Hypoglycemia increased AMPKα2 gene expression in male, but not female rats; Ghrh-R siRNA pretreatment amplified this transcript profile in INS-injected rats of each sex." (PMID 40688570, 2025). "In addition to thorough education, modern insulin analogs, and higher target glucose levels, the use of CGM is crucial for managing impaired awareness of hypoglycemia." (PMID 40061402, 2025). "As insulin clearance is carried out by the kidneys, reduced eGFR in CKD may result in hypoglycemia; hence, the modifications of insulin should be contemplated to reach glycemic targets." (PMID 40861717, 2025). "Case 1 suggests that C-peptide maintenance through infliximab results in improved control without significant hypoglycemia while on insulin." (PMID 41282287, 2025). "The diagnosis of CHI was established based on persistent severe hypoglycemia, inappropriately elevated insulin and C-peptide levels during hypoglycemia, absence of ketogenesis, a positive glucagon stimulation test, and exclusion of other causes of NH." (PMID 40904956, 2025). "Continuous glucose monitors (CGM) and automated insulin delivery (AID) systems have not only led to improved quality of life but also better glycemic outcomes and reduced incidence of hospitalizations for severe hypoglycemia and diabetic ketoacidosis (DKA)." (PMID 40434817, 2025). "Hirata’s syndrome associated with the use of alpha-lipoic acid was described for the first time in Italy in six patients not previously treated with insulin but hospitalized for severe hypoglycemia." (PMID 40564126, 2025). "Since rapid-acting insulins used in insulin pumps last for several hours, a reduction in the basal insulin rate is, in many instances, not sufficient to avoid hypoglycemia in connection with physical activity." (PMID 38629871, 2025). "Insulin suspension via pump alone should not be used to treat hypoglycaemia because it does not work quickly enough." (PMID 39432570, 2025). "We present a case of Hirata’s disease in a 53-year-old Caucasian female not previously exposed to insulin, that manifested as recurrent hypoglycemia." (PMID 39968421, 2025). "Since diagnosis, she was treated with insulin glargine without any short-acting insulin, yet persistently suffered from hypoglycemia." (PMID 40395699, 2025). "Following hospital discharge, the patient used insulin sporadically, without experiencing hypoglycemia." (PMID 39935661, 2025). "Insulin and GLP-1RAs are the most widely used biomacromolecular drugs for hypoglycemia." (PMID 40006605, 2025). "Low-dose insulin infusion (0.05 units/kg/hour) demonstrated comparable efficacy to standard-dose (0.1 units/kg/hour) in resolving pediatric DKA, but with lower rates of hypoglycemia (3.3% vs. 13.3%) and hypokalemia (30% vs. 43.3%)." (PMID 41262789, 2025). "Elevated insulin and C-peptide with low ketones during hypoglycemia indicate functional, not structural, hyperinsulinism." (PMID 41531556, 2025). "A notable feature of this system is its dynamic insulin sensitivity adjustment along with Predictive Low-Glucose Suspend (PLGS) functionality, enabling it to suspend basal insulin delivery during both hypoglycemia and when a rapid reduction in glycemic levels is signaled by the glucose sensor." (PMID 41010993, 2025). "Several clinical trials and observational studies have shown a decrease in glycated hemoglobin (HbA1c) and a lower incidence of hypoglycemia using CIPII, also reducing fasting insulin levels, in comparison with subcutaneous insulin delivery through CSII and MDI." (PMID 40995084, 2025).
Hypoglycemia (continued). "In the present cases, SGLT2i and insulin were used concomitantly, but with careful self-monitoring of blood glucose, resulting in no episodes of severe hypoglycemia." (PMID 40704640, 2025). "Since metformin does not stimulate insulin secretion, patients receiving metformin monotherapy typically do not experience hypoglycemia under normal circumstances." (PMID 40963686, 2025). "The aim of the present systematic review and meta-analysis was to expand examination of the effects of GLP-1RA in addition to insulin treatment in patients with T1D with regard to glycemic control, body weight, TID, time-in-range (TIR), and incidence of severe hypoglycemia." (PMID 40760325, 2025). "Additionally, we assessed the effects of the addition of a GLP-1RA on body weight, total insulin dose, TIR, and incidence of severe hypoglycemia." (PMID 40760325, 2025). "Subcutaneous insulin protocols, low-dose insulin infusions, and balanced crystalloids optimize DKA management, while lower dextrose concentrations may suffice for hypoglycemia." (PMID 41262789, 2025). "Hypoglycemia diminished this gene profile in old female, but not old male rats; patterns of ERβ gene expression following INS injection were unaffected by prior Ghrh siRNA pretreatment." (PMID 40613376, 2025). "It is likely that combining insulin and glucose-sensor enzymes would mimic key aspects of physiological regulation; however, muscle-based systems may not achieve the rapid, pulsatile insulin kinetics of native β-cells, posing a hypoglycemia risk if expression is not tightly controlled." (PMID 41226304, 2025). "Endogenous hyperinsulinemic hypoglycemia syndrome (EHHS) is a rare disorder characterized by inappropriate insulin secretion independent of glucose levels, leading to recurrent episodes of severe hypoglycemia." (PMID 40981133, 2025). "The β-cell microtubule network has a complex architecture and is nondirectional, which provides insulin granules at the cell periphery for rapid secretion response, yet to avoid oversecretion and subsequent hypoglycemia." (PMID 41182903, 2025). "These challenges for insulin patients are further illustrated by the higher reported reasons of non-adherence in the insulin group, which are the fear of hypoglycemia and the discomfort of injection." (PMID 40959330, 2025). "Metformin presents itself as a potentially effective oral substitute to insulin in the treatment of GDM, demonstrating its capacity to regulate blood sugar levels, prevent weight gain during pregnancy, and decrease the occurrence of neonatal hypoglycemia." (PMID 39860070, 2025). "They reduce hepatic glucose production, increase insulin sensitivity, and delay intestinal glucose absorption but do not stimulate insulin secretion or contribute to hypoglycaemia." (PMID 40651878, 2025). "It is noteworthy that five of the six affected patients were concurrently using insulin; despite this, no treatment discontinuations resulted from hypoglycemia." (PMID 41517430, 2025). "The Leuven I trial showed that IIT, a strict glycemic control strategy, was effective in reducing mortality in critically ill patients, however, severe hypoglycemia was increased by IIT, including in the VISEP (Volume Substitution and Insulin Therapy in Severe Sepsis) and Glucontrol studies." (PMID 40400655, 2025). "After administering 2 units of rapid-acting insulin, he finished the marathon in 3 h and 38 min without hypoglycemia." (PMID 40217942, 2025). "PLGS-enabled pumps such as the Medtronic 640G and 740G (The producer: Medtronic MiniMed, Minneapolis, MN, USA) suspend insulin delivery when glucose levels fall and restart once they normalize, providing strong protection against hypoglycemia." (PMID 41156556, 2025). "Research indicates that patients who have undergone RYGB with PBH demonstrate significantly elevated postprandial GLP‐1 levels and marked insulin surges compared to those who do not experience hypoglycemia." (PMID 41206858, 2025).
Hypoglycemia (continued). "Lifestyle modifications and traditional therapeutic approaches, like metformin, sulfonylureas, and insulin, often fail to achieve adequate glycemic control without adverse effects such as weight gain and hypoglycemia." (PMID 40870388, 2025). ",27, 28, 29, 30 It has been proposed that they should be continued when the incidence of hypoglycaemia is low, for example, when insulin or other glucose-lowering agents are not used, or when sulfonylureas have been used for longer than 3 months." (PMID 40651878, 2025). "We measured serum insulin levels weekly, and as expected, these were increased but did not increase the frequency of hypoglycemia." (PMID 40492016, 2025). "Upon cessation of exogenous insulin, the two individuals described in this article experienced relief from nocturnal and fasting hypoglycemia; thus, hormone therapy was not initiated." (PMID 41234224, 2025). "It is interesting to note that in the HE-Ob-CS group, the improvement in insulin sensitivity was not accompanied by marked hypoglycemia, unlike in the Ob-CS group." (PMID 41471698, 2025). "Due to the subsequent impaired insulin absorption and frequent severe hypoglycemia events, in May 2022 patient was referred to our unit to implant a DiaPort system for CIPII therapy using an external insulin pump (Accu Chek®)." (PMID 40995084, 2025). "These types of drugs have lower risks of hypoglycemia, because the secretion of insulin is not directly induced." (PMID 39899133, 2025). "Reduced insulin and C-peptide levels during hypoglycemia effectively ruled out insulinoma and exogenous insulin use, indicating a non-insulin-mediated mechanism." (PMID 41333493, 2025). "Because incretin action is glucose-dependent, these drugs improve blood glucose control without provoking hypoglycaemia - a persistent problem for many patients treated with sulfonylureas and, later, insulin." (PMID 41262822, 2025). "Mothers described a lack of sleep due to hypoglycaemia episodes and constant insulin pump or continuous glucose monitoring alarms." (PMID 41051982, 2025). "This review did not identify a significant advantage of SC insulin in the reduction in hypoglycemia, hypokalemia, or other outcomes between the two approaches." (PMID 41227190, 2025). "Studies show the occurrence of hypoglycemia in about 25 % of DKA treatments using high doses of insulin and indicate that this frequency could decrease with continuous insulin infusion at lower doses." (PMID 40037551, 2025). "However, comprehensive comparisons with insulin degludec regarding continuous glucose monitoring (CGM) metrics and hypoglycaemia outcomes remain limited." (PMID 40509887, 2025). "Lupanine enhances glucose-dependent insulin secretion without inducing hypoglycemia in rodent models, and thermopsine-derived conjugates inhibit coronavirus RNA-dependent RNA polymerase at low micromolar concentrations." (PMID 41515341, 2025). "In this study, the intranasal administration of insulin did not significantly decrease blood glucose levels in treated mice, even though the insulin dosage used would typically induce hypoglycemia when administered subcutaneously or intraperitoneally to mice." (PMID 40699683, 2025). "Clinically significant or severe hypoglycaemia rates remained below one episode per person-year of exposure in all trials except ONWARDS 4, where the rates were higher, as expected since this trial used a basal-bolus insulin regimen." (PMID 40186685, 2025). "Hypoglycemia occurred in one-third of participants with dapagliflozin (almost all of whom were also receiving insulin), mainly asymptomatically; no hypoglycemia events led to discontinuation of treatment." (PMID 41001667, 2025). "This modest reduction is meaningful and clinically relevant as it was achieved with a substantially reduced insulin dose and without an increase in hypoglycemia." (PMID 41268167, 2025).
Hypoglycemia (continued). "In select studies, mild hypoglycemia was more evident in subjects taking insulin icodec versus the comparator but no other concerns were identified." (PMID 40156735, 2025). "By blocking GLP-1R, avexitide reduces postprandial insulin peaks and prevents hypoglycemia without significantly altering basal glucose levels." (PMID 41226200, 2025). "While effective in congenital hyperinsulinism, its use in autonomic-mediated hypoglycemia is limited because insulin secretion is not persistently excessive." (PMID 41531556, 2025). "There is no direct correlation between the severity of hypoglycemia and circulating insulin concentration." (PMID 40904956, 2025). "Unlike the SC depot which continues to release insulin, this rapid hepatic extraction reduces the prolonged systemic hyperinsulinemia responsible for late hypoglycemia." (PMID 41471078, 2025). "The mechanism of hypoglycemia with ginseng is not fully established, with both enhanced insulin sensitization and insulin secretion being proposed mechanisms." (PMID 41331795, 2025). "Continuous glucose monitoring (CGM) and personalized dosing regimens are employed to mitigate hypoglycemia risks, given the non-autoimmune etiology and variable insulin requirements." (PMID 40869431, 2025). "NICTH diagnosis is supported by demonstrating non-insulin mediated hypoglycemia, with appropriately low levels of proinsulin, c-peptide, and insulin, and inappropriately low ketone levels." (PMID 40648766, 2025). "Alpelisib, an α-selective phosphatidylinositol 3-kinase (PI3K) inhibitor, plays a crucial role in insulin signaling, and has been used in patients with refractory congenital hyperinsulinism and non-islet cell tumor hypoglycemia." (PMID 41561059, 2025). "Since blood glucose levels in euDKA typically remain near normal or only mildly elevated (usually <250 mg/dL), a major clinical concern is determining the effective mode of insulin administration without inducing hypoglycemia." (PMID 40941597, 2025). "The risk of hypoglycemia with tirzepatide remains low, consistent with other GLP-1 receptor agonists, particularly in the absence of concomitant Insulin or sulfonylureas." (PMID 41405657, 2025). "The reduction in 24-hour, nighttime and daytime TBR < 54 mg/dl (level 2 hypoglycemia) was insignificant between the Control IQ and standard insulin therapy, these results is not comparable with the previous finding from the previous study." (PMID 40790781, 2025). "In view of the clinically significant spontaneous hypoglycemia episodes with capillary blood glucose (CBG) as low as 1.6 mmol/L, further evaluations with venous glucose, serum insulin, serum C-peptide, and beta-hydroxybutyrate were conducted when capillary glucose was < 3mmol/L." (PMID 40375949, 2025). "Standard insulin injection practices mainly include proper storage of insulin, timely administration, correct IIT, rotation of injection sites, safe disposal of needles, management of hypoglycemia, and side effects." (PMID 40376558, 2025). "Hyperinsulinemia (i.e., elevated insulin without hypoglycemia) is a common metabolic feature of PCOS that worsens its reproductive symptoms by exacerbating pituitary hormone imbalances and increasing levels of bioactive androgens." (PMID 40013621, 2025). "Although glibenclamide has long been a considerable alternative to insulin, recent studies have reported that it can cross the placenta, stimulate fetal insulin secretion, and increase the risks of macrosomia (LGA) and neonatal hypoglycemia in a dose-dependent manner." (PMID 41237113, 2025). "The lack of consistent mortality benefit and excess hypoglycemia in the Brunkhorst trial on intensified insulin therapy in severe sepsis led to early termination, emphasizing the dangers of overly aggressive glucose lowering." (PMID 41109933, 2025). "First, it incorporates multiobjective reward shaping, allowing the model to optimize not just TIR but also insulin efficiency, glycemic stability, and hypoglycemia prevention." (PMID 40614090, 2025).